RAC1 (Rac family small GTPase 1)
Diseases named in the same sentence as RAC1 in open-access papers (continued):
Sharing a sentence is not in itself a finding about the gene and the disease.
urothelial carcinoma (5 papers, 2012 to 2022). A malignant neoplasm derived from the transitional epithelium of the urinary tract (urinary bladder, ureter, urethra, or renal pelvis). "CSTF2 induces 3′‐UTR shortening of Rac family small GTPase 1 (RAC1) to exacerbate cellular malignancy in urothelial carcinoma." (PMID 34586744, 2021). "Moreover, Rac1 activity and increased levels of PAK1 expression were associated with lymph nodes metastasis in urothelial carcinoma." (PMID 32351958, 2020).
urothelial carcinoma of the bladder (5 papers, 2021 to 2022). "As a vital cleavage/polyadenylation factor, CSTF2 can shorten the length of 3’UTR RAC1 in human urothelial carcinoma of the bladder by mediating slow transcriptional elongation at RAC1." (PMID 34195183, 2021). "A bioinformatic analysis of mRNA from patients with urothelial carcinoma of the bladder has revealed the presence of a shorter 3’-UTR (3′-untranslated region) isoform of Rac1 and this specific isoform was associated with an upregulation of Rac1 protein expression." (PMID 35740379, 2022). "Studies have shown that CSTF2 induces shortening of RAC1 3′-UTR and promotes urothelial carcinoma of the bladder." (PMID 35370655, 2022). "The RAC1 short-3' UTR isoform promotes the oncogenic and metastatic capacities in urothelial bladder carcinoma cells both in vitro and in vivo." (PMID 35013128, 2022).
acute kidney injury (4 papers, 2016 to 2024). Sudden and sustained deterioration of the kidney function characterized by decreased glomerular filtration rate, increased serum creatinine or oliguria. "RAC1 gene could influence susceptibility to renal failure by altering the activity and expression of Rac1 which is the member of the Rho family of small GTP-binding proteins." (PMID 26841219, 2016). "Some studies have indicated that RAC1 gene has a critical role in the regulation of the gene expression involved in Rac1 activation and mineralocorticoid-receptor activation, which would be associated with the renal failure." (PMID 26841219, 2016). "RAC1 gene could influence susceptibility to renal failure by altering the activity and expression of Rac1, which is a member of the Rho family of small GTP-binding proteins." (PMID 26841219, 2016). "Sema3A enhances LPS-induced acute kidney injury by increasing Rac1 (a key factor for activation of NF-κB) and p65 and augments LPS-induced macrophage activation and cytokine production in a plexin-A4–dependent manner." (PMID 34039431, 2021). "Moreover, TRPM2 mediates acute kidney injury via a mechanism that involves the activation of Rac Family Small GTPase 1 (RAC1), oxidative stress, and mitochondrial apoptotic pathways." (PMID 37275121, 2023).
amyotrophic lateral sclerosis (4 papers, 2011 to 2019). Amyotrophic lateral sclerosis (ALS) is a neurodegenerative disease characterized by progressive muscular paralysis reflecting degeneration of motor neurons in the primary motor cortex, corticospinal tracts, brainstem and spinal cord. "The study results displayed the relevance of Rac1 dysregulation in the pathogenesis of Amyotrophic Lateral Sclerosis (ALS)." (PMID 28028462, 2016). "Rac1’s role in amyotrophic lateral sclerosis (ALS) disease seems to involve Rab5 activity." (PMID 31035701, 2019).
Arrhythmia (4 papers, 2016 to 2025). Any cardiac rhythm other than the normal sinus rhythm. "Early discovery that RhoGDIα overexpression in cardiomyocytes decreased Rho GTPase activity and induced arrhythmias and atrioventricular block led to the study of Rac1 in cardiac arrhythmias." (PMID 41333012, 2025). "Blockade of Rac1 activation may represent a new paradigm for the treatment of cardiac arrhythmia in ischaemic heart disease." (PMID 27222313, 2016). "Inhibition of Rac1 decreases ROS production, RyR2 oxidation, and cardiac arrhythmia during I/R." (PMID 27222313, 2016). "Collectively, our study demonstrated that inhibition of Rac1 activation protects against arrhythmogenesis during myocardial I/R, and may represent a new paradigm for the treatment of cardiac arrhythmia in ischemic heart disease." (PMID 27222313, 2016). "Thus, inhibition of Rac1 may have a therapeutic potential for clinical treatment of cardiac arrhythmia in ischaemic heart disease." (PMID 27222313, 2016). "Thus, Rac1 may represent a potential therapeutic target for the treatment of cardiac arrhythmia in ischaemic heart disease." (PMID 27222313, 2016).
autism spectrum disorder (4 papers, 2017 to 2021). A spectrum of developmental disorders that includes autism, and Asperger syndrome. "Moreover, SHANK2 and SHANK3 have been shown to be causative genes for autism spectrum disorders, possibly through the regulation of RAC1 function." (PMID 32616021, 2020). "Recent studies suggest that autism spectrum disorder (ASD)-related behavioral phenotypes in animal models of ASD can be produced by dysregulation of Rac1’s control of actin polymerization at glutamatergic synapses." (PMID 28928363, 2017).
autoimmune disease (4 papers, 2010 to 2023). A disorder resulting from loss of function or tissue destruction of an organ or multiple organs, arising from humoral or cellular immune responses of the individual to their own tissue constituents. "Rac1 is an important target for reducing inflammatory reaction and treating autoimmune diseases under pathological conditions." (PMID 37049739, 2023). "Among them, RAC1 was found to be involved in autoimmune diseases by regulating ERK1/2 signaling." (PMID 37280674, 2023). "Aberrant Rac1 activity is closely related to the development of autoimmune diseases." (PMID 37049739, 2023). "Moreover, RAC1 activation can be directly induced by IL17A and RAC1 inhibitory peptide has been found to suppress T cell activation and autoantibody production in autoimmune disease." (PMID 25544849, 2014). "The data suggest that targeting of Rac1 with the Rac1 carboxy-terminal inhibitory peptide may suppress T-cell activation and autoantibody production in autoimmune disease." (PMID 20053277, 2010).
breast infiltrating ductal carcinoma (4 papers, 2018 to 2024). "The disruption of the activity of RhoA or Rac1/Cdc42 is associated with malignancy, and in invasive breast ductal carcinoma, the overexpression of either RhoA or Rac1 have been associated with worse prognosis." (PMID 29535813, 2018). "Jensen and co-workers, by using an anti-RAC1-GTP antibody, performed the immunohistochemical detection of RAC1-GTP in tissue sections of invasive ductal breast carcinoma from patients." (PMID 34831012, 2021).
breast invasive carcinoma (4 papers, 2015 to 2022). "Furthermore, regulation of Rac1 signaling by ARF1 which directly interact with miR-96 in the regulatory network is associated with invasive breast cancer cells." (PMID 25874214, 2015). "We found a significant negative correlation between ZNF750 and RAC1 in all the breast invasive carcinoma datasets analysed." (PMID 33298895, 2020). "In this study, we demonstrate that levels of β1 integrin and Rac1 expression were greater in breast IMPC than in invasive breast carcinoma of no specific type and paraneoplastic benign breast tissue." (PMID 29435106, 2018).
cardiomyopathy (4 papers, 2022 to 2025). A disease of the heart muscle or myocardium proper. "In vivo, overexpression of Rac1(G12V) in the mouse heart results in a cardiomyopathy phenotype characterized by hypertrophy or dilation." (PMID 37524688, 2023). "Thus, mice expressing constitutively active Rac1 developed cardiomyopathy and exhibited a post-ischemic contractile dysfunction." (PMID 35230541, 2022). "However, loss of Rac1 or other identified zDHHC3 targets Gαq/11 or galectin-1 does not diminish zDHHC3-induced cardiomyopathy, suggesting multiple effectors and pathways promoting decompensation with sustained zDHHC3 activity." (PMID 37926281, 2023). "Our previous work confirmed the validity of the Rac1–NADPH oxidase pathway in ELMO1-driven ROS production, as oral inhibition of Rac (EHT1864) or Nox4 each partially mitigated cardiomyopathy, while pan-NADPH oxidase inhibition (VAS3947) markedly prevented it." (PMID 41300434, 2025). "However, deletion of Rac1 in the heart did not alter the progression of Zdhhc3 overexpression–driven cardiomyopathy." (PMID 37926281, 2023).
colorectal tumors (4 papers, 2002 to 2020). "Interestingly, Rac1b, an alternative splicing variant of Rac1, is an oncoprotein increased in the subgroup of colorectal tumors and is necessary to maintain the viability of tumor cells." (PMID 33072610, 2020). "APC stimulates the activity of the Cdc42- and Rac1-specific guanine nucleotide exchange factor Asef and promotes the migration and invasion of colorectal tumor cells." (PMID 24244701, 2013). "In addition, we show that expression of the rac1 splice variant rac1b, which was shown to be enhanced in colorectal tumours, is not tumour-specific increased in breast tissue." (PMID 12237774, 2002).
Crohn disease (4 papers, 2013 to 2019). A gastrointestinal disorder characterized by chronic inflammation involving all layers of the intestinal wall, noncaseating granulomas affecting the intestinal wall and regional lymph nodes, and transmural fibrosis. "However, the functional consequences of knocking out Rac1 gene exon-3b, especially changes in the incidences of tumors and inflammatory diseases, such as Crohn's disease, still need to be evaluated carefully in Rac1b−/− rats." (PMID 26918455, 2016). "We found that two RAC1 gain PDCs were resistant to immunosuppressive agent azathioprine (also named thiopurine and 6-MP), which have been widely used in a variety of clinical conditions for decades, such as Crohn’s disease, rheumatic diseases, organ transplantation, and so on41–44." (PMID 31700061, 2019). "Five genes (NME6 from the purine/thiopurine network, PLCB2 of the RAC1 network, and HVCN1, CTSS, and DEF8) correlated with the Harvey-Bradshaw index of Crohn’s disease activity." (PMID 23437289, 2013).
endometriosis (4 papers, 2017 to 2026). The growth of functional endometrial tissue in anatomic sites outside the uterine body. "In hESC cells co-cultured with gestational epithelial endometriosis organoids, SFRP1, CDC42, RAC1, and WASF3 were upregulated, while PTK2B was downregulated, reflecting the miRNA cargo of ENDO-GEST-derived EVs." (PMID 42282918, 2026). "RAC1 is essential for the integrin-induced MAPK activation and its up-regulation contributes to the activation of MAPK pathway in patients with endometriosis." (PMID 28835770, 2017).
Impaired glucose tolerance (4 papers, 2016 to 2021). An abnormal resistance to glucose, i.e., a reduction in the ability to maintain glucose levels in the blood stream within normal limits following oral or intravenous administration of glucose. "Impaired glucose tolerance and higher plasma insulin concentrations after intraperitoneal glucose injection in muscle-specific rac1 knockout (m-rac1-KO) mice actually demonstrate the physiological importance of Rac1 in insulin action in skeletal muscle." (PMID 30735546, 2019). "Indeed, impaired glucose tolerance and higher plasma insulin concentrations after intraperitoneal glucose injection were observed in muscle-specific rac1 knockout (m-rac1-KO) mice." (PMID 27163697, 2016). "Moreover, muscle-specific rac1 knockout mice actually showed impaired glucose tolerance and higher plasma insulin concentrations after intraperitoneal glucose injection, providing evidence that Rac1 plays a physiologically important role in insulin-dependent glucose uptake in skeletal muscle." (PMID 34639094, 2021). "Moreover, impaired glucose tolerance and higher plasma insulin concentrations after intraperitoneal glucose injection were observed in muscle-specific rac1 knockout mice, demonstrating that Rac1 actually plays a physiologically important role in insulin action in skeletal muscle." (PMID 31683681, 2019).
liver disease (4 papers, 2014 to 2025). "Another study exploring the role of circRNA in radiation-induced liver disease showed that circRSF1 enhanced RAC1 expression by acting as miR-146a-5p sponge to inhibit miR-146a-5p, and thus increased the cell viability, and promoted fibrotic and inflammatory phenotype of irradiated LX2 cells." (PMID 36187780, 2022). "Our results demonstrate the significance of Rac1/JNK in cirrhosis or HCC and the potential utilization of Rac1/JNK targeting for liver diseases therapy." (PMID 25950481, 2015).
mantle cell lymphoma (4 papers, 2018 to 2022). Mantle cell lymphoma is a rare form of malignant non-Hodgkin lymphoma affecting B lymphocytes in the lymph nodes in a region called the ``mantle zone''. "In other cases, such as in mantle cell lymphoma (MCL), over-expression of RAC1 usually leads to shorter survival and poorer prognosis for patients." (PMID 36552804, 2022). "In mantle cell lymphoma (MCL) RAC1 overexpression leads to its increased activity and is correlated with a shorter survival in patients." (PMID 31248017, 2019). "In hematological malignancies, overexpression of Rac1 mRNA was observed in multiple myeloma (MM) as well as in mantle cell lymphoma (MCL)." (PMID 30558116, 2018).
Multiple Myeloma (4 papers, 2011 to 2025). "RAC1 is involved in the adhesion of myeloma cells in the BM, which contributes to drug resistance and invasiveness." (PMID 40308607, 2025). "In the apoptosis cluster, RAC1 was a gene of interest as little is known about the role of RAC1 in myeloma and its progression." (PMID 21375780, 2011).
myeloid leukemia (4 papers, 2013 to 2023). A clonal proliferation of myeloid cells and their precursors in the bone marrow, peripheral blood, and spleen. "In myeloid leukemia, oncogenic Kras leads to RAC1 activation, causing NADPH activation and resulting in ROS production, which in turn activates inflammation-related effects." (PMID 36451866, 2022). "krasG12D-induced NLRP3 activation is dependent on RAC1-mediated accumulation of ROS in myeloid leukemia cells." (PMID 37081882, 2023). "In agreement with our observations in mice, patient-derived myeloid leukemia cells exhibit KRAS/RAC1/ROS/NLRP3/IL-1β axis activity." (PMID 32246016, 2020). "This work revealed the existence of KRAS/RAC1/ROS/NLRP3/IL-1β pathway in human myeloid leukemia." (PMID 37081882, 2023). "Our laboratory previously established the association and reciprocal regulation of Rac1 and SET/I2PP2A (inhibitor 2 of protein phosphatase 2A), a nuclear proto-oncogene which, as a protein-fusion with Nup214, is associated with myeloid leukemia." (PMID 23874639, 2013).
myeloproliferative neoplasm (4 papers, 2015 to 2024). A clonal hematopoietic stem cell disorder, characterized by proliferation in the bone marrow of one or more of the myeloid (i.e., granulocytic, erythroid, megakaryocytic, and mast cell) lineages. "Nevertheless, Rac1/Rac2 double knockout mice develop CML-like myeloproliferative neoplasms among other tumors, which are most likely attributable to Rac3 activity." (PMID 30558116, 2018). "Although Rac1 has proven to be an interesting molecular target in AML and other myeloproliferative diseases, Rac1 also plays an important role in normal hematopoietic cell homeostasis." (PMID 29228706, 2017). "Furthermore, oncogenic KRAS mutations were shown to induce NLRP3 via upstream activation of RAC1 GTPase and subsequent generation of reactive oxygen species (ROS), implicating upregulation of the RAC1/ROS/NLRP3/IL-1β axis as a crucial event in myeloproliferative disorders." (PMID 39223663, 2024).
non-small cell lung adenocarcinoma (4 papers, 2011 to 2023). Type of epithelial lung cancer arising from glandular origin. "Here we have investigated the hypothesis that Rac1, a Rho GTPase implicated in cancer cell proliferation and invasion, is critical for tumor initiation and metastasis of human non-small cell lung adenocarcinoma (NSCLA)." (PMID 21347385, 2011). "A functional relationship between RAC1 and CSCs was suggested from findings in non-small cell lung adenocarcinoma (NSCLAC)." (PMID 34771704, 2021). "Blockade of Rac1 suppresses the CSC proliferation and metastasis in human non-small cell lung adenocarcinoma." (PMID 27557508, 2016).
pancreatic adenocarcinoma (4 papers, 2015 to 2023). "Finally, 8 differentially expressed genes (ERLIN1, HMGA2, FAM110B, EGFR, MCM2, BCL2L1, E2F1 and RAC1) were considered to be significantly negatively associated with survival (P < 0.05) time of pancreatic adenocarcinoma patients." (PMID 29596435, 2018). "The Rho GTPase-activating protein 25 (ARHGAP25) has been shown to specifically inactivate the Rho family GTPase Rac1, which plays an important role in pancreatic adenocarcinoma (PAAD) progression." (PMID 33994864, 2021). "Significantly, we also found the roles of BCL2L1, E2F1 and RAC1 in tumor differentiation and survival prediction of pancreatic adenocarcinoma." (PMID 29596435, 2018). "It is worth mentioning that increased expression of RAC1 has been found in pancreatic adenocarcinoma and is correlated with patient prognosis." (PMID 29596435, 2018). "Herein, we found that BCL2L1, E2F1, RAC1 and STAT1 were expressed in pancreatic adenocarcinoma, which was consistent with previous reports." (PMID 29596435, 2018). "According to the KEGG pathway analysis, we found that several tumor differentiation related genes (such as BCL2L1, E2F1, RAC1 and STAT1) were remarkably enriched in pancreatic adenocarcinoma signaling pathway." (PMID 29596435, 2018).
prostate tumor (4 papers, 2014 to 2021). "Rac3 and Rac1 have opposite effects in PC-3 prostate tumor cell diapedesis; while depletion of Rac1 inhibits diapedesis, Rac3 knockdown promotes diapedesis, showing that Rac1 is required for PC-3 cell diapedesis across a bone marrow endothelial cell layer, while Rac3 inhibits tumor cell diapedesis." (PMID 31514269, 2019). "Al‐Azayzih observed that stimulation with TGFβ1 induced prostate tumour cell scattering and increased expression of Snail and N‐cadherin through TRAF6‐mediated activation of Rac1/Pak1 pathway." (PMID 29193723, 2018). "TGFβ1 stimulation induces prostate tumour cell scattering and increases the expression levels of Snail and N‐cadherin through the TRAF6‐mediated activation of Rac1/Pak1 pathway." (PMID 29193723, 2018).
renal fibrosis (4 papers, 2013 to 2025). A final common manifestation of a wide variety of chronic kidney diseases characterized by glomerulosclerosis and tubulointerstitial fibrosis. "The concentration of systemically administered UPARANT was measured in the plasma, in kidney and liver extracts and UPARANT effects on dysregulated uPAR pathway, αvβ3 integrin/Rac‐1 activity, renal fibrosis and kidney morphology were determined." (PMID 30426662, 2019). "Furthermore, inhibition of Rac1 activity by Rhein not only reduces oxidative stress but also affects downstream signaling pathways involved in EMT and renal fibrosis, such as the β-catenin pathway." (PMID 40766752, 2025).